EGFR (epidermal growth factor receptor)
Diseases named in the same sentence as EGFR in open-access papers (continued):
Sharing a sentence is not in itself a finding about the gene and the disease.
lung cancer (continued). "Recently, several studies showed that EMT was observed in EGFR mutant lung cancers with acquired resistance to EGFR TKIs (2 of 37)." (PMID 22970367, 2012). "The EGFR-TKIs erlotinib and gefitinib have also shown dramatic effects against EGFR-mutant lung cancer and have been approved for second-line therapy in patients with metastatic NSCLC." (PMID 23198146, 2012). "As with many targeted therapeutics, acquired resistance to EGFR TKIs is of growing concern in lung cancer." (PMID 22788954, 2012). "EGFR-positive lung cancer patients are more responsive to Iressa and Tarceva, which are classified as EGFR tyrosine kinase inhibitors." (PMID 22890830, 2012). "More specifically, pathway genes that show associations with EGFR or MET were examined in detail, because EGFR and MET are among the best-studied growth signals in lung cancer patients." (PMID 22211244, 2012). "Since aberrant EGFR signaling is implicated with the initiation and progression of lung cancer, we first assessed SP frequency and expression of ABCG2 in the presence of an antagonistic antibody against EGFR." (PMID 23009336, 2012). "Therapeutic strategies being implemented to target EGFR, miRNAs, autophagy and cancer stem cells are discussed, including the use of curcumin in lung cancer." (PMID 22489192, 2012). "EGFR knockdown by siRNA further decreases the cell growth of lung cancer cells that are treated with TKIs or cetuximab alone, confirming that single agent drug targeting does not achieve a maximal biological effect." (PMID 22436374, 2012). "Combined targeting of ER and EGFR in NSCLC has been proved to enhance antiproliferative effects in the treatment of lung cancer." (PMID 22363346, 2012). "EGFR tyrosine kinase inhibitors (EGFR-TKIs) produce a dramatic clinical response in a significant proportion of patients with lung cancer." (PMID 22784503, 2012). "Meanwhile, MM-121 combined with the anti-EGFR antibody cetuximab showed a synergic effect in a lung cancer model." (PMID 23198146, 2012). "Somatic mutations in the tyrosine kinase domain of the Epidermal Growth Factor Receptor (EGFR) gene emerged as one of the most relevant targets for lung cancer treatment." (PMID 22848739, 2012). "KRAS is downstream of EGFR, and hence tumors that contain KRAS mutations were found to be resistant to EGFR TKIs which makes KRAS a good marker for patients who should be excluded from EGFR TKI treatment and are accepted for gene testing of lung cancer." (PMID 26316937, 2012). "Epidermal growth factor receptor-tyrosine kinase inhibitors (EGFR-TKIs), such as gefitinib and erlotinib, show favorable response to EGFR mutant lung cancer in some populations of NSCLC patients." (PMID 22336239, 2012). "In lung cancer, although EGFR-TKI treatment leads to significant responses in patients with EGFR gene mutations, acquired resistance to these drugs inevitably occurs." (PMID 23198146, 2012). "Although EGFR MoAbs have been under clinical investigation in lung cancer, the frequently observed somatic kinase domain activating mutations affecting the EGFR oncogene has led to widespread clinical use of EGFR tyrosine kinase inhibitors (TKIs)." (PMID 23320170, 2012). "Resistance to EGFR TKIs in lung cancers and glioblastomas was overcome by inhibition of Met activity." (PMID 22788954, 2012). "In 1991, the first phase I trial of a mouse monoclonal antibody (IgG1) against EGFR was completed in advanced lung cancer patients and demonstrated antibody uptake at the tumor site." (PMID 23150825, 2012). "Except for paclitaxel, these 874 lung cancer patients were also treated with one or several of the following drugs: platinum compounds, gemcitabine, EGFR inhibitors or etoposide." (PMID 23006423, 2012). "A recent study by Frenkel, Gazdar and colleagues concluded that depsipeptide co-administered with EGFR inhibitors gave a substantial advantage over EGFR inhibitors alone in xenograft models of lung cancer." (PMID 22158273, 2012).
lung cancer (continued). "Nevertheless, our results suggest that MUC1 functions as a mediator that bridges CS-induced pulmonary inflammation and lung cancer development by potentiating EGFR-mediated survival signaling." (PMID 22457794, 2012). "On the other hand, overexpression of β1-integrin has been shown to correlate with acquired resistance to EGFR inhibitors in lung cancer." (PMID 22053213, 2011). "We evaluated the effects of rabdocoetsin B on lung cancer cells expressing wide-type (WT) or mutant EGFR." (PMID 21655278, 2011). "Numerous studies have shown that dual inhibition of IGF-1R and EGFR can be synergistic in moderating growth and migration of prostate cancer, lung cancer, and colorectal cancer." (PMID 24212944, 2011). "The EGFR is one of the most frequently overexpressed proteins in various cancers including lung cancer, and signalling through this receptor is related to tumour progression and resistance to most treatments." (PMID 22095231, 2011). "Erlotinib is a targeted drug that inhibits signalling through the EGFR and thereby prolongs survival of a subgroup of lung cancer patients treated with this drug." (PMID 22095231, 2011). "In conclusion, we found that autophagy can be activated by EGFR-TKIs in lung cancer cells and inhibition of autophagy augmented the growth inhibitory effect of EGFR-TKIs." (PMID 21655094, 2011). "It was similarly reported in studies with the utilization of the immunohistochemical assay that EGFR expression was very low in normal tissue but often over-expressed in lung cancer tissue." (PMID 21385353, 2011). "Unexpectedly, we found that the C225-NP was selectively cytotoxic for EGFR-overexpressing lung cancer cells beyond what would be expected from the unconjugated antibody." (PMID 22087216, 2011). "We used human lung cancer cells with different levels of EGFR expression and changed the surface composition of NP to elucidate mechanisms of these interactions." (PMID 22087216, 2011). "To develop more effective therapies for lung cancer we have combined the anti-EGFR antibody (Clone 225) as a molecular therapeutic with hybrid plasmonic magnetic nanoparticles (NP) and tested on non-small cell lung cancer (NSCLC) cells." (PMID 22087216, 2011). "In terms of the EGFR is highly correlated with the tumor progression in lung cancer, wild-type EGFR is the main population among the NSCLC cases, and EGFR T790M results in TKIs resistance." (PMID 21858220, 2011). "Of the 198 patients with nonsmall cell lung cancer, 52 patients (26.3%) had EGFR-TKI-sensitive EGFR mutations, and one patient had an EGFR-TKI-resistant mutation (T790M) with an EGFR-TKI-sensitive mutation (Exon 19 deletion)." (PMID 22191026, 2011). "Targeted therapeutic approaches for lung cancer, including treatment with TKIs for EGFR or the fusion protein EML4-ALK, have seen substantial progress over the last few years." (PMID 21847121, 2011). "Our initial goal was to use C225-NP as an imaging agent targeted to EGFR overexpressing lung cancer cells." (PMID 22087216, 2011). "We have previously developed 11C-erlotinib as a new positron emission tomography (PET) tracer and shown that it accumulates in epidermal growth factor receptor (EGFR)-positive lung cancer xenografts in mice." (PMID 22095231, 2011). "mTOR inhibition has also been known to reverse in vitro acquired resistance to endocrine therapy and EGFR inhibitors of breast and lung cancers, respectively." (PMID 21364753, 2011). "In summary, our results show that ART exerts antitumor effects through the down-regulation of EGFR and its downstream factor Akt in lung cancer cells." (PMID 22183882, 2011). "EGFR-mutant lung cancers eventually become resistant to anti-EGFR therapies, and then progress rapidly." (PMID 21699731, 2011). "For example, FK-228, a depsipeptide HDAC inhibitor, is reported to decreasethe expression of EGFR in lung cancer cells." (PMID 21464950, 2011).
lung cancer (continued). "Erlotinib (Tarceva, Hoffmann-La Roche Ltd., Basel, Switzerland) is a small molecule tyrosine kinase inhibitor targeting EGFR (epidermal growth factor receptor) in lung cancer." (PMID 21970335, 2011). "Many factors including EGFR, HIF-1A, AKT1 and RAF-1 are known to be regulated by Hsp90 and their abnormal expression level is often associated with lung cancers." (PMID 21283735, 2011). "Consistently, we found that autophagy can be activated by gefitinib and erlotinib in lung cancer and promote cellular survival in the target therapy using EGFR-TKIs." (PMID 21655094, 2011). "Gefitinib is a reversible epidermal growth factor receptor tyrosine kinase inhibitor (EGFR-TKI) used for the treatment of nonsmall cell lung cancer patients." (PMID 22191026, 2011). "We have here shown that MET associates with EGFR, HER2, HER3, and RET, and that these heterodimerisation partners of MET are highly phosphorylated in lung cancer cells positive for MET amplification." (PMID 21847121, 2011). "EGFR expression was significantly increased in dysplastic cells, indicating that EGFR pathway involves in lung cancer development." (PMID 21385353, 2011). "We confirmed biochemically and morphologically that autophagy can be activated by gefitinib or erlotinib, two well-used EGFR-TKIs, in two independent lung cancer cell lines." (PMID 21655094, 2011). "Molecular aberrations on the EGFR pathway are the most commonly studied predictive biomarkers of response/resistance to targeted agents in lung cancer." (PMID 21444946, 2011). "In lung carcinoma, epidermal growth factor receptor (EGFR) is more abundantly expressed than in adjacent normal lung." (PMID 22272089, 2011). "EGFR is expressed in a variety of human tumors, including gliomas and carcinomas of the lung, colon, head and neck, pancreas, breast, ovary, bladder, and kidney." (PMID 21403829, 2011). "Gene amplification of EGFR has been described in oligodendrogliomas, glioblastomas, lung carcinomas, gastric carcinomas, and recently, in breast carcinomas." (PMID 21730982, 2011). "Accordingly, a clinical definition of acquired resistance to EGFR TKIs has been established for unifying therapy and studying this subset of lung cancer." (PMID 21165163, 2010). "This strongly suggests that in lung cancer, global patterns of tyrosine phosphorylation are at least as dependent on MET activation as they are on EGFR mutation." (PMID 20976048, 2010). "Bim expression was significantly induced by EGFR TKI inhibition in gefitinib-sensitive EGFR-mutant lung cancer cells through both transcriptional and post-translational mechanisms." (PMID 21165163, 2010). "Targeting key EGFR-downstream signalling pathways should be an alternative approach for overcoming resistance to erlotinib or gefitinib in lung cancers." (PMID 21165163, 2010). "If self-sufficiency in growth is a hallmark of cancer, then additional receptor tyrosine kinases capable of signaling for growth, which render EGFR autocrine signaling redundant, can account for the reduced effectiveness of EGFR TKIs in lung cancer." (PMID 21152424, 2010). "Clinical and biological evidence suggest that EGFR signaling is only one important signaling pathway in lung cancer." (PMID 21152424, 2010). "Notable examples include HER2 amplification in breast cancer, EGFR amplification in lung cancer, and MYCN amplification in neuroblastoma." (PMID 20569491, 2010). "Epidermal growth factor receptor (EGFR) is highly expressed in many malignancies, including head and neck cancer, lung cancer, and colorectal cancer." (PMID 20184776, 2010). "Conversely, 89.2% Taiwanese lung cancer patients have an identifiable mutation in either c-CBL, MET or EGFR or a combination of the three genes." (PMID 20126411, 2010). "In summary, circulating ligands for the c-Met and EGFR pathways are both elevated in many lung cancer patients, and signaling from these ligands is compensatory." (PMID 21390244, 2010).
lung cancer (continued). "We have also previously demonstrated a reinforcing loop of c-Met-EGFR cross-activation initiated by HGF in lung cancer, that occurs via COX-2 activation and involves direct phosphorylation of c-Met by EGFR ligands." (PMID 21390244, 2010). "Inhibition of key signalling mediators downstream of EGFR should also lead to clinical effects in the treatment of lung cancer with robust EGFR activity." (PMID 21165163, 2010). "Mass spectrometry (MS) coupled with anti-phosphotyrosine antibodies identified different patterns of tyrosine kinase signaling in lung cancer cells and tumors, and this approach was able to identify cells driven by oncogenic EGFR, PDGFR, and ALK." (PMID 20976048, 2010). "EGFR-expressing lung cancer cell lines were able to bind cetuximab and initiate complement activation by the classical pathway, irrespective of the mutational status of EGFR." (PMID 20529262, 2010). "In lung cancer this has been demonstrated in the context of systemic chemotherapy and/or EGFR-TK therapy." (PMID 20942962, 2010). "Here, evidence is presented that the location of RT-qPCR primers is critical in the evaluation of the epidermal growth factor receptor (EGFR) small interfering RNA (siRNA) efficacy, even up to 72 hrs post-treatment in lung cancer cells." (PMID 21369532, 2010). "Erlotinib and gefitinib, two EGFR-targeted agents, have been shown to be relevant drugs for lung cancer treatment." (PMID 20459769, 2010). "We next determined if SH2 domain binding correlated with the sensitivity of lung cancer cell lines to erlotinib, a small molecule EGFR kinase inhibitor." (PMID 20976048, 2010). "A study with Vandetanib reported that when radiation therapy is combined concomitantly with VEGFR2 and EGFR blockade, a significant enhancement of anti-angiogenic, anti-vascular, and anti-tumour effects is seen in an orthotopic model of lung cancer." (PMID 20628392, 2010). "In lung cancers, sensitivity to EGFR inhibition by small molecules such as gefitinib and erlotinib is associated with EGFR mutation." (PMID 20037743, 2010). "For example, aberrant EGFR signaling in glioblastoma, lung cancer and MCF10A cells led to enhanced IL-6 production and signaling." (PMID 20929542, 2010). "In the last few years, many clinical trials have proven the efficacy of EGFR-targeted therapies in the management of several cancers, including breast, colon, pancreas, head and neck, renal, and lung carcinomas." (PMID 20843314, 2010). "Several agent classes have been used to improve survival in a variety of tumor types, and EGFR-disruptive therapies have had promising results in lung cancer in specific patient populations." (PMID 20130810, 2009). "Lung cancers are frequently heterogeneous with significant variability of EGFR copy number within the same tumor." (PMID 19889201, 2009). "KRAS mutations have been reported by several independent groups to be negatively associated with response to EGFR tyrosine kinase inhibitors in lung cancer and EGFR-directed antibodies in colon cancer." (PMID 19636423, 2009). "The concept ofmanipulation of EGFR in the treatment of epithelial malignancies such ascolorectal and lung cancers has actually been envisaged since the mid 1960s." (PMID 19365583, 2009). "With the potential importance of ErbB receptor inhibitors for lung cancer treatment, and with multiple ErbB receptors activated in these cell lines, we investigated their sensitivity to the dual EGFR/Her2 kinase inhibitor GW2974 in proliferation assays." (PMID 19240716, 2009). "In animal models, an EGFR inhibitor, gefitinib, prevents carcinogenesis of gallbladder and lung cancer, and reduces the incidence of metastasis of prostate carcinoma cells." (PMID 19319137, 2009).
lung cancer (continued). "The vandetanib IC50 for the PC-9 lung cancer cell line, which is sensitive to EGFR inhibitors, was reported earlier to be 0.14 μM." (PMID 19319137, 2009). "Both the epidermal growth factor receptor signaling pathway and microRNA (miRNA) play an important role in lung cancer development and progression." (PMID 19702827, 2009). "Distinction between EGFR gene amplification and high chromosome 7 polysomy is required, till the role of increased EGFR copy number in NSCLC patients in contributing to lung cancer oncogenesis and susceptibility to TKIs will be definitely established." (PMID 19889201, 2009). "It has been reported that in nonsmall cell lung cancer (NSCLC), mutations within the EGFR tyrosine kinase domain, mainly in exons 18, 19 and 21, confer sensitivity to TKIs." (PMID 20066159, 2009). "Among these pathways, epidermal growth factor receptor (EGFR) signaling appears to be particularly important for epithelial malignancies, including lung cancer." (PMID 19702827, 2009). "High EGFR protein expression was observed in several types of cancer including breast, bladder, colon and lung carcinomas." (PMID 19178753, 2009). "Based on these findings, we postulate that efficient endocytosis of ligand-induced EGFR is closely related to EGFR-tyrosine kinase inhibitor sensitivity of human lung cancer cell lines." (PMID 18492291, 2008). "In a recent paper dealing with expression profiling of epidermal growth factor receptor/KRAS pathway activation in lung cancer two groups of ADC were individualized, one being a bronchial-type, the other an alveolar-type." (PMID 18549475, 2008). "Retrospective studies found that after treatment with gefitinib or erlotinib, lung cancer patients with EGFR exon 19 deletions had a longer overall survival when compared with patients with EGFR L858R." (PMID 18542074, 2008). "To examine any change in gene expression in serum before and one month after surgical treatment in the same patients and to examine their significance as tumor markers, we quantified hTERT mRNA and EGFR mRNA expression in 9 patients with lung cancer." (PMID 21892326, 2008). "On the other hand, there are some reports to show that overexpression of HER-2 is an independent prognostic factor of survival and to be a combinatorial target in lung cancer, using an EGFR tyrosine kinase inhibitor together with HER-2 dimerization inhibitors." (PMID 19055823, 2008). "This article reviews EGFR-targeted therapies in use and in development, with a focus on the role of EGFR in the pathophysiology of head and neck and lung cancer, and new concepts being investigated to improve outcomes with these agents." (PMID 18836658, 2008). "Immunoprecipitation studies of the MET and EGFR under single- or dual-ligand stimulation confirmed the presence of receptor cross-activation between MET and EGFR in these lung cancer cell lines." (PMID 19238632, 2008). "EGFR expression was observed in 64.5 % of invasive cancers, all adenocarcinomas, and in 13% percent of cases high polysomy as defined in lung cancer was found." (PMID 18182111, 2008). "The sensitivity/specificity in lung cancer diagnosis was 71.8%/72.5% for hTERT mRNA and 60.8%/62.5% for EGFR mRNA respectively." (PMID 21892326, 2008). "The sensitivity of CEA, SCC, CYFRA, EGFR mRNA and hTERT mRNA for lung cancer was 40.1%, 58.9%, 48.8%, 60.8% and 71.8%, respectively." (PMID 21892326, 2008).